PINK1 (PTEN induced kinase 1)
Diseases named in the same sentence as PINK1 in open-access papers (continued):
Sharing a sentence is not in itself a finding about the gene and the disease.
cancer (continued). "The positive correlations between the expression of PINK1, SRC, BECN1, and OPTN and drug sensitivity suggest that higher levels of these genes are associated with increased vulnerability of cancer cells to treatment." (PMID 39859167, 2025). "PINK1 plays a role in regulating various physiological and pathological processes in cancer cells, such as cytoplasmic homeostasis, cell survival, and cell death." (PMID 39859167, 2025). "We then explored the methylation levels (beta-values, HumanMethylation450) of MAP1LC3A, OPTN, PINK1, PRKN, SRC, BNIP3L, and BECN1 in pan-cancer and their association with gene expression and the immune cell infiltrates." (PMID 39859167, 2025). "In contrast, in lung cancer, PINK1 expression is upregulated, which promotes chemoresistance and cancer proliferation." (PMID 40943612, 2025). "Dysregulation of mitophagy regulators, such as PINK1, Parkin, BNIP3, NIX, and FUNDC1, have been implicated in cancer progression." (PMID 41306556, 2025). "The results revealed that the expression of Parkin or PINK1 was negatively correlated with the sensitivity of cancer cells to the ferroptosis inducer erastin, suggesting that cancer cells with defective mitophagy are sensitive to ferroptosis." (PMID 39679775, 2025). "While the role of PI3K and PINK1 in various cancer types is still not fully understood, previous studies have shown that PI3K acts as a master regulator of brain metastasis, facilitating metastatic colonization." (PMID 40243539, 2025). "Inhibition of PINK1/Parkin-dependent mitophagy enhances the sensitivity of multidrug-resistant cancer cells to B5G1, a novel betulinic acid analog." (PMID 40855568, 2025). "In cancer cells, hypoxia-induced HIF-1 upregulates the mitochondrial ribosomal protein (MRPL52), promoting PINK1/Parkin-dependent mitochondrial autophagy to clear ROS and protect cancer cells." (PMID 40723842, 2025). "PINK1 was found to play a role in the pathophysiological processes in cancer cells, including cytoplasmic homeostasis, and cell survival and death." (PMID 39921807, 2025). "PINK1-mediated mitophagy confers cancer cells with the ability to survive chemotherapy, whereas inhibiting mitophagy restores chemosensitivity in chemotherapy-treated ESCC cells." (PMID 39723259, 2024). "To examine the effect of inflammatory cytokines, we treated the cells with HMGB1 and TNFα for 48 h at concentrations equivalent to those in the cancer ascites (50 μg/mL and 35 pg/mL, respectively) and examined the changes in 4HNE, PINK1, and Parkin." (PMID 39000167, 2024). "In endometrial cancer, abnormal PINK1/parkin pathway expression promotes cancer occurrence and development." (PMID 38711526, 2024). "Mitochondrial autophagy process inhibition involved in the PINK1/parkin pathway induces apoptosis and inhibits cancer cell growth and proliferation." (PMID 38711526, 2024). "PINK1-mediated mitochondrial autophagy can promote oxidative phosphorylation and redox homeostasis and induce drug resistance persistence in cancer cells." (PMID 39144972, 2024). "Flavagline (FL3) inhibits cancer cell development by mediating Parkin/PTEN-induced kinase 1 (PINK1) dependent mitophagy." (PMID 38262996, 2024). "Key pathways, including the classic PINK1-Parkin and the hypoxia-driven BNIP3/Nix and FUNDC1 pathways, are implicated in the metabolic reconfiguration of cancer cells, particularly affecting glycolysis." (PMID 38913914, 2024). "Initially, a pan-cancer analysis revealed that Pink1 was highly expressed in patients with various types of cancer." (PMID 39834805, 2024). "In cancer, mitochondrial autophagy experiences impairment, affecting mitochondrial autophagy receptors and adapters, including PINK1, Parkin, BNIP3, BNIP3L/NIX, and p62/SQSTM1, along with associated signaling pathways." (PMID 38505747, 2024). "In this study, by analysing data from public databases, we found differential expression of PINK1 in a variety of cancers." (PMID 36823640, 2023).
cancer (continued). "PINK1 regulates cell survival, stress resistance, mitochondrial homeostasis, and the cell cycle, all of which are key signaling pathways misused by cancer cells during tumor initiation and progression." (PMID 36819105, 2023). "Several mitophagy adaptors, such as a parkin, PINK1, bifunctional mitochondrial protein (BNIP3), autophagic indicator (P62/SQSTM1) and signaling pathways (nuclear factor (erythroid-derived 2)-like 2 (Nrf2)/PINK1/Parkin pathway), are impaired in cancer." (PMID 37375256, 2023). "PTEN-induced kinase 1 (PINK1), a serine/threonine kinase, was originally discovered in cancer cells." (PMID 36823640, 2023). "PINK1, as well as E3 ubiquitin ligase Parkin, are defense mechanisms by which cancer cells resist mitochondrial apoptosis." (PMID 36830954, 2023). "Previous studies have shown that PINK1 can directly activate AKT via activation of mTORC2 to enhance invasiveness of cancer cells." (PMID 37940999, 2023). "Initially identified as a key participant in the mitochondrial quality control system via mitophagy, an autophagic process, further evidence suggests that PINK1 is also involved in various subcellular pools to regulate cancer cell survival and chemoresistance." (PMID 37940999, 2023). "The results of our study should stimulate additional research into PINK1 as a potential master regulator of cellular metabolism, aging, and cancer." (PMID 36830954, 2023). "PINK1 is a complex regulator in cancer etiology, regulated in part by the early and late stages of the disease pathogenesis." (PMID 36830954, 2023). "PINK1 has cytoprotective effects by improving cancer cell proliferation and survival and prevents apoptosis in cancer cells." (PMID 36823640, 2023). "Eventually, PINK1 has the potential as a biomarker for prognosis and the immune response across cancers." (PMID 37047483, 2023). "Discovered in 2001, PTEN-induced putative kinase 1 (PINK1) is a serine/threonine kinase whose upregulation was first observed as a consequence of PTEN activity in cancer cells." (PMID 37940999, 2023). "The mechanisms underlying PINK1 protection and resistance in cancer cells indicate that PINK1 is a target for cancer therapy and specifically for NSCLC." (PMID 36909198, 2023). "ARIH1 E3 ubiquitin ligase is recruited to mitochondria by PINK1 to eliminate mitophagy of polyubiquitinated, damaged mitochondria in response to chemotherapeutic drug-induced death, thereby protecting cancer cells." (PMID 36831455, 2023). "Summarizing the obtained results, PINK1 can be used as a potential target in the treatment of cancer." (PMID 36830954, 2023). "PINK1–Parkin is one of the main ubiquitin-dependent signaling pathways of mitophagy and is known to be involved in neurodegenerative diseases and cancer." (PMID 36831455, 2023). "PINK1 promotes tumor survival, protects cancer cells from different cytotoxic agents, and exerts its biological function through oxidative stress." (PMID 35707364, 2022). "Our data validate that MUC1/ATAD3A/Pink1 axis-mediated mitophagy constitutes a novel mechanism for maintaining the malignancy of cancer cells, providing a novel therapeutic approach for MUC1-positive cancers." (PMID 36289190, 2022). "Along with the mitochondrial function of PINK1, the role of PINK1 in regulating cell cycle has also been reported, which is more likely to relate to tumor and cancer cells in which PINK1 expression is noticeably altered." (PMID 35874823, 2022). "Considering the dispensable role of Parkin and PINK1 in basal mitophagy in vivo, further analysis of the role of Gp78-dependent basal mitophagy in tissue development and cancer progression is warranted." (PMID 36284011, 2022). "B5G1, a novel betulinic acid analog, sensitizes multidrug-resistant cancer cells via inhibiting PINK1/ Parkin -dependent mitophagy." (PMID 35326612, 2022).
cancer (continued). "PINK1-dependent or BNIP3/NIX-mediated mitophagy has been reported to promote chemoresistance in CSCs of various cancers." (PMID 35725817, 2022). "Several E3 ligases trigger mitophagy in cancer cells in a Pink1-dependent but Parkin-independent manner, such as Ariadne RBR E3 Ub protein ligase 1 (ARIH1) and seven in absentia homolog 1 (SIAH-1)." (PMID 36289190, 2022). "The PINK1/Parkin pathway is the well-studied ubiquitin-mediated system involved in cancer chemoresistance." (PMID 35326612, 2022). "The data are consistent with work showing that overexpression of PINK1 can lead to increase in cancer cell growth." (PMID 34138755, 2021). "Compounds, including derivatives of betulinic acid, have been found to trigger ROS and PINK1–Parkin-mediated mitophagy to induce apoptosis in multi-drug-resistant cancer cells." (PMID 34361072, 2021). "Through parallel high-throughput RNA interference screening, it was found that in the context of DNA mismatch repair defects in cancer, PINK1 silencing led to increased ROS production and subsequent oxidative DNA damage in the nucleus and mitochondria." (PMID 34751247, 2021). "The most well-studied ubiquitin-mediated pathway involved in cancer chemoresistance is the PINK1-Parkin pathway." (PMID 33946271, 2021). "It has recently been reported that multidrug-resistant cancer cells become more sensitive to chemotherapy drugs when PINK1/Parkin-dependent mitophagy is inhibited." (PMID 33929971, 2021). "Many studies have reported that mitophagy is activated through the PINK1/Parkin signaling pathway in cancer cells." (PMID 33929971, 2021). "The previous study has suggested that Samm50-mediated mitophagy is dependent on the Pink1-Parkin pathway under cancer conditions." (PMID 34631840, 2021). "Together, these interactions provide potential mechanisms to underpin observations that PINK1 promotes cell survival against various pro-apoptotic stimuli in multiple cell types, including cancer and neuronal models." (PMID 34897410, 2021). "PTEN-induced increase in PINK1 and decrease in PI3K/AKT have been found in PD and several cancers, suggesting that PINK1 plays an important pathological function." (PMID 33912571, 2021). "LIHC represents a cancer in which patients had good survival with high PINK1 expression, while LUSC represents a cancer in which patients had poor survival with high PINK1 expression." (PMID 33244455, 2020). "These analyses further confirmed that PINK1 expression plays an important role in immune infiltration in cancers such as LIHC and LUSC." (PMID 33244455, 2020). "We used the online TIMER database to explore the correlation between PINK1 expression and the levels of six kinds of immune infiltrates across cancers." (PMID 33244455, 2020). "Second, we used Kaplan-Meier Plotter to further analyze the prognostic value of PINK1 in different types of cancers." (PMID 33244455, 2020). "The results showed that PINK1 was significantly correlated with tumor purity in 18 out of 39 cancer types." (PMID 33244455, 2020). "Although there was a significant prognostic value of PINK1 expression across cancers, PINK1 played a protective or detrimental role in different kinds of cancers." (PMID 33244455, 2020). "PINK1 expression was significantly correlated with nine cancer types and played a protective role in ESCA, HNSC, LIHC, PADC, OV, and TGCT." (PMID 33244455, 2020). "We discovered that there was a significant prognostic value of PINK1 expression in seven cancer types: colorectal, ovarian, blood, brain, breast, lung, and soft tissue cancers." (PMID 33244455, 2020). "To confirm the role of PINK1 in cancers, we analyzed the prognosis of patients according to PINK1 expression in different kinds of cancer with data from various databases." (PMID 33244455, 2020).
cancer (continued). "Over 20 unique datasets revealed that PINK1 had lower mRNA expression in different kinds of cancers than in normal tissues." (PMID 33244455, 2020). "Under hypoxia, HIF-1α can upregulate the expression of HEY1 and then recruit corepressors to inhibit the transcriptional activity of PINK1, reducing mitochondrial mass and promoting the growth of cancer cells." (PMID 32928258, 2020). "The E3 ubiquitin ligase ARIH1 is widely expressed in many cancers, such as breast cancer and lung adenocarcinoma, and induces mitophagy in a PINK1-dependent manner." (PMID 33375363, 2020). "PINK1/Parkin- dependent mitophagy plays an important role in mitochondrial homeostasis, and the modulation of PINK1/Parkin-mediated mitophagy alters the sensitivity of multidrug-resistant cancer cells to anticancer agents." (PMID 32796618, 2020). "To identify the potential mechanisms of PINK1 expression across cancers, we used LIHC as an example." (PMID 33244455, 2020). "Our results also find that the immune infiltration levels of antigen presenting cells such as macrophages and B cells are significantly correlated with the PINK1 expression level in cancers." (PMID 33244455, 2020). "Recent studies have already showed some possible mechanisms deciphering why PINK1 expression correlated with different prognoses and immune infiltration in pan-cancer." (PMID 33244455, 2020). "The expression of BECN1 (participates in macrophagy) and PINK1 (participates in mitophagy) was reduced at every stage of cancer development." (PMID 33322704, 2020). "We used the online TIMER database to explore the correlation between PINK1 expression and the infiltration levels of six immune cell types across cancers." (PMID 33244455, 2020). "The mitophagy-related protein PINK1 can work as a biomarker for prognosis and the immune response across cancers." (PMID 33244455, 2020). "PINK1-mediated excessive mitophagy promotes survival of cancer cells resistant to chemotherapy, implying that suppression of mitophagy can restore the chemo-sensitivity of ESCC cells." (PMID 32587855, 2020). "In conclusion, the mitophagy-related protein PINK1 is significantly correlated with prognosis and immune infiltration across cancers, especially in LIHC and LUSC." (PMID 33244455, 2020). "In the current study, we used multiple databases, including Oncomine, PrognoScan, Kaplan-Meier Plotter, GEPIA, TIMER, and cBioportal, to investigate the PINK1 expression distribution and its immunological and prognostic role across cancers." (PMID 33244455, 2020). "Recent studies has shown that ectopic expression of PINK1 plays a dual role in cancer development and drug treatment." (PMID 33280610, 2020). "Next, we analyzed the prognostic value of PINK1 expression across cancers in PrognoScan, Kaplan-Meier Plotter, and GEPIA." (PMID 33244455, 2020). "Research on PINK1 revealed that its many functions go beyond neuroprotection; this protein is involved in various diseases, including cancer." (PMID 33066407, 2020). "We identified PINK1 expression across cancers and compared its mRNA expression with that in corresponding normal tissues based on data from the Oncomine database." (PMID 33244455, 2020). "The cytoprotective and chemo-resistant function for PINK1 has been highlighted by studies supporting PINK1 as a target in cancer therapeutics." (PMID 33615312, 2020). "PINK1 resulted to be altered in several cancers such as ovarian cancer, glioblastoma, and neuroblastoma and the same came from BNIP3 screening." (PMID 31210843, 2019). "In addition to that, PARK2 and PINK1, loss-of-function variations of which lead to familial PD, have recently been shown to negatively regulate the Warburg effect, a switch from mitochondrial respiration to aerobic glycolysis when oxygen supply is normal in cancer." (PMID 31843010, 2019). "In summary, these data show that Mfn2 ubiquitylation and p62 recruitment to mitochondria take part in PINK1/Parkin-mediated mitophagy in B5G1-treated resistant cancer cells." (PMID 30850585, 2019).